CD4 (CD4 molecule)
Diseases named in the same sentence as CD4 in open-access papers (continued):
Sharing a sentence is not in itself a finding about the gene and the disease.
co-infection (continued). "The results of this study showed that higher age, male gender, external migrant patients, co-infection with hepatitis B and C viruses, rural residency and homosexual transmission method have a negative association with CD4 cell count." (PMID 33766121, 2021). "It has a suppressive effect on the CD4+ T cells as seen in the HIV/HBV co infection." (PMID 33889269, 2021). "Coinfection or adjacent infection of epidermal LCs (or CD11c+ epi-cDC2s) may provide the conduit for HIV to reach dermal CD4+ T cells." (PMID 33668777, 2021). "Previous studies suggested that co-infection can facilitate the rate of malaria transmission by the process of CD4 cell activation, up-regulation of pro-inflammatory and cytokine production, and T-cell activation resulting in a reduction in the immune response." (PMID 34404814, 2021). "Another remarkable aspect of this study is represented by the fact that co-infection with CoSV was significantly more common in enterovirus-infected PLHIV with CD4+ T cell counts below 200 cells/μL, indicating the potential role of CoSV as an opportunistic agent." (PMID 32079128, 2020). "Therefore, the main objective of our study was to determine if the impact of pre-HAART CD4+ T-lymphocyte count and percentage on pediatric immune recovery varied based on TB co-infection status." (PMID 33059622, 2020). "In this study, CD4 <200 cells/μl, advanced WHO clinical stage, higher HIV viral load, age ≥40 years, and coinfection with HBV at baseline was identified as the risk factors for cytopenia in the multivariate analysis, a finding consistent with that of the previous studies." (PMID 32090076, 2020). "Median CD4 level was 386 /μL (IQR 299–518) at diagnosis of co-infection." (PMID 32443596, 2020). "The median CD4 count in this study was 536 cells/μL [IQR:169–709] which is similar to a previous study that found a median CD4 count of 584 cells/μL [IQR: 396–775] in HIV/HCV co-infection." (PMID 33059627, 2020). "Similarly, a previous study showed that pharmacist involvement improved therapeutic efficacy as evidenced by the lower number of CD4-positive lymphocytes and reduced rate of superinfection (co-infection) within 6 months." (PMID 32377369, 2020). "As such, we sought to evaluate whether co-infection with the parasitic helminth Schistosoma mansoni (SM) modifies CD4 T cell lineage profiles in a cohort of HIV-uninfected adults in Kisumu, Kenya." (PMID 32117277, 2020). "In high pathogen burden settings where co-infection is common and reoccurring, plasticity of antigen-specific CD4 T cell responses may be important in preserving Mtb-specific TH1 responses." (PMID 32117277, 2020). "Besides, CD4+ T cell immunoreactivity was found to be greater than CD8+ T cell immunoreactivity in the co-infections which occurred by both agents." (PMID 30823555, 2019). "Next, we sought to determine whether co-infection with HIV significantly modifies inhibitory receptor expression profiles of Mtb-specific CD4 T cells." (PMID 31497018, 2019). "Together these data provide new insights into the phenotype of Mtb-specific CD4 T cells in the setting of co-infection with Mtb and HIV and provide rationale for future studies to evaluate the utility of targeting BTLA and HVEM signaling pathways to enhance protective immunity to Mtb." (PMID 31497018, 2019). "While all VL patients with HIV co-infection may benefit from secondary prophylaxis, those with CD4 <200 cells/μL and previous history of treatment should be prioritized for secondary prophylaxis." (PMID 30789910, 2019). "TB co-infection has shown to contribute to the higher rate of low CD4+ T cells to HIV therapy." (PMID 31805857, 2019). "However, CD4+ T lymphocyte count was significantly lower in HIV/HBV co-infection compared to HIV/HCV and HIV mono-infection respectively." (PMID 31323077, 2019).
co-infection (continued). "In univariate analyses, we first assessed the contribution of cART exposure (months of therapy), specifically looking at protease inhibitor (PI) exposure, tenofovir (TDF) exposure, HCV co-infection, CD4 counts, current HIV viral load, age, LTL, BMI, smoking, and parity to BMD at the three sites." (PMID 29783641, 2018). "In our study, 3 of the HIV-positive patients had CD4+ cell counts <350 cells/μL, which might explain the worse visual outcomes associated with HIV co-infection." (PMID 29350138, 2018). "Interestingly, only CD4+ T cells showed the most prominent induction of IFNγ expression and increase in IFNγ+ numbers upon co‐infection." (PMID 29113976, 2018). "Furthermore, HIV-HBV coinfections, especially those with a high HBV DNA load, are associated with lower CD4+ T-cell counts before treatment initiation." (PMID 30192795, 2018). "Considering evidence from previous research and pathophysiological mechanisms, a detrimental effect of helminth coinfection on CD4 counts recovery may be expected." (PMID 30332404, 2018). "Risk factors like HIV‐1‐non‐B subtype, high HIV‐load and low CD4 cell count, insufficient adherence and co‐infections influencing the drug levels can possibly facilitate the selection of DTG‐resistant variants, in our case the R263K and the G118R substitutions." (PMID 30362663, 2018). "This low CD4 count in the advent of malaria in the first trimester could contribute to the increasing rate of HBV infections leading to the high malaria/HBV coinfection in the first pregnancy." (PMID 30344800, 2018). "Taken together, CD4+ T cells are the major contributors of higher splenic IFNγ during co‐infection." (PMID 29113976, 2018). "Moreover, activation (CD38+HLADR- subset) of CD8 T-cells was associated with presence of HCV coinfection in a multivariate analysis correcting by HIV-pVL and CD4 counts, drug abuse and gender." (PMID 28323897, 2017). "Since this is one of the parameters associated with CD4 counts, this suggests that presence of HCV coinfection could impact on HIV immunological progression, although follow up studies are necessary to confirm this hypothesis." (PMID 28323897, 2017). "In vitro co-infection of a given CD4+ T-cell by both HTLV-1 and HIV-1 has been reported." (PMID 29267225, 2017). "Co-infection may have treatment implications because of CD4 counts being preserved in these patients." (PMID 39583012, 2017). "Furthermore, our finding is also similar to other studies in Ghana and South East Nigeria suggesting that HIV and malaria co-infection significantly decreases CD4 count." (PMID 28346490, 2017). "Malaria and HIV co-infection significantly reduces CD4 count." (PMID 28346490, 2017). "Importantly, we show that while helminth-reactive CD4+ T cells are unable to produce Th2 cytokines in a co-infection, they still express significant amounts of IFN-γ after restimulation with helminth antigen." (PMID 28791259, 2017). "Finally, we examined group x time interaction (CD4 count*co-infection status*ART status) as the difference in change-from-baseline/first CD4 count between the four ‘treatment’ groups." (PMID 28346490, 2017). "In cases of leishmania and HIV co-infection, CD4 <200cells/μl and malnutrition could lead to reactivation of latent infections (reactivation leishmaniasis)." (PMID 28841834, 2017). "Also, large studies done in Africa and Europe have reported impaired CD4+ outcomes due to HBV co-infection after varying periods of ART." (PMID 27251610, 2016). "Although we characterized longitudinally the phenotype and function of Mtb-specific CD4 T-cells in 21 individuals undergoing treatment for HIV-TB co-infection and replicated our findings in a second cohort of HIV negative individuals, both cohorts were modest in size." (PMID 27367521, 2016).
co-infection (continued). "When compared with subjects with baseline CD4 counts <50 cells/μL, those with counts in the 50–200 cells/μL range (OR = 0.76, 95%CI = 0.60–0.98) and in the 351–500 cells/μL range (OR = 0.31, 95%CI = 0.11–0.85) were at decreased risk of HCV co-infection." (PMID 26933963, 2016). "It is possible that lung-resident subsets of CD4 and γδ T cells may respond differently to co-infection than cells from the blood, or that effects of the in vivo lung microenvironment may alter IL-17 production and the inflammatory response." (PMID 26942409, 2016). "HIV co-infection occurred in 178 patients (83%) with a median CD4 count 88 cells/ml3 (IQR 27–218)." (PMID 27812140, 2016). "Plain chest radiography (and in affluent settings, also CT) are the mainstays for diagnostic imaging of pulmonary TB, but are often nonspecific and unable to provide a definitive diagnosis due to the heterogeneous presentation, particularly in case of HIV co-infection when CD4 counts are low." (PMID 27077068, 2016). "Since CTC clinic files are housed at ORCI, future studies should further utilize these files to understand additional factors contributing to NADC incidence such as HIV treatment details, CD4 count, co-infections, height and weight for BMI calculations, and more thorough substance use data." (PMID 27895703, 2016). "Our hypothesis is that the immunophenotype (cytokine secretion profile and expression of PD-1) of the MTB-specific CD4+ T-cell response reflects the manifest failure of MTB containment in HIV co-infection i. e. active TB." (PMID 26756579, 2016). "However, the association was not confirmed when fitting a multivariate time dependent model including also age, gender, CD4 cell count, presence of Hepatitis B or/and C virus co-infection and intravenous drug use." (PMID 26442127, 2015). "One third of the TB/HIV coinfection in Africa occur at CD4 count < 200 cells/μL." (PMID 25966339, 2015). "HIV coinfection rates were greater than 70% for all types of meningitis; the proportion of patients with CD4 cell counts below 100 cells/mm3 was 100% (9/9) for cryptococcal meningitis, 50% (5/10) for viral meningitis, 33% (5/15) for bacterial meningitis, and 0% (0/22) for TB meningitis." (PMID 26491454, 2015). "In a model adjusted for age, CD4 lymphocyte count, and co-infection with high-risk types, the association was no longer observed (aPR = 0.90, 95 % CI 0.67–1.21)." (PMID 26100400, 2015). "The lack of activity of acyclovir against HIV in our experimental co-infection model could be explained by the fact that we infected the CD4+ T cells with both viruses simultaneously." (PMID 26132818, 2015). "Interestingly, in addition to HIV co-infection active TB disease was linked to further down regulation of CD27 and increased capacity of Mip-1β production in CMVpp65-specific CD4+ T cells." (PMID 25974183, 2015). "In bivariate Cox regression analysis, sex, marital status, education level, functional status, WHO clinical stage, BMI, CD4 count, Anemia, cotrimoxazole prophylaxis, INH prophylaxis, TB co-infection, and ART adherence were all associated with survival (P < 0.05)." (PMID 26889319, 2015). "Although there was an increase in CD4+ T-cell count (+38.0 cells/μl) in all treated helminth/HIV co-infection, in contrast to the expected benefits of deworming the difference was not statistically significant (P = 0.16) after 15 weeks of antihelminthic treatment." (PMID 26415705, 2015). "Among ART-naïve HIV patients, those with H. pylori co-infection had higher CD4 T cell counts (312 vs. 189 cells/μl, p<0.0001), higher CD4/CD8 ratios (0.31 vs. 0.19, p<0.0001) and lower HIV-1 viral loads (4.92 vs. 5.21 log10 copies/ml, p = 0.006) compared to those without H. pylori co-infection." (PMID 26599971, 2015). "A Cochrane analysis on the treatment of HIV positive with helminth co-infection concluded that anti-helminthic treatment may slow the decline in CD4 cell count." (PMID 25768005, 2015).
co-infection (continued). "An independent T-test was used for correlation of oral lesions with CD4+ count and a χ2 test was used for analysis of the relationship of co-infection with hepatitis B virus (HBV), sexual contact, route of transmission, history of drug abuse, and history of incarceration." (PMID 25745611, 2015). "The effects of helminth coinfection on CD4 counts in HIV-coinfected subjects are also conflicting." (PMID 25793933, 2015). "These CMV-specific CD4+ cells were more differentiated in HIV co-infection than PPD and/or EBV." (PMID 26417433, 2015). "Furthermore CD4+ PPD-specific cells secreting IFN-γ and IL-2 and expressing CD127 were relatively less frequent in HIV co-infection indicating another potential mechanism of the loss of this key subset." (PMID 26417433, 2015). "Similarly, gene sets including carbohydrate, lipid, amino acid, and nucleotide metabolism were also up-regulated in the co-infection group in CD4+ T cells." (PMID 25623235, 2015). "Another possible explanation for the more rapid CD4 cell decline among IDUs could be the high rate of co-infection with HCV, as previous studies have shown deteriorated clinical outcome among HIV-positive individuals with HCV antibodies." (PMID 24388495, 2014). "A total of 147 women (including 13 with coinfection) interrupted treatment 6 months postpartum when the risk of breastfeeding transmission was ceased, while the remaining 162 (including 15 with coinfection), who had baseline CD4+ < 350/mm3, continued antiretrovirals indefinitely." (PMID 24708626, 2014). "Collectively, we show that multiple immune regulatory pathways are induced in HCV/HIV coinfection including FoxP+ Tregs, PD-1, and CTLA-4 in significant association with HIV-associated CD4 T cell loss and with apparent suppression of effector T cell responses against HIV but not HCV." (PMID 25071758, 2014). "Patients with VL and HIV co-infection usually have a CD4 count less than 200 cells/μl, may have involvement of atypical sites, like the eye, and are prone to a relapsing VL course despite appropriate treatment." (PMID 26530344, 2014). "Based on carefully collected program data over a period of ten years, we report on the prevalence of HBV and HCV co-infection, and the effect on ART response in term of CD4 cell count recovery, all-cause mortality and ART-related drug toxicity in adult patients on ART in Cambodia." (PMID 24533106, 2014). "Consequently, CD4 cell measurement is the sole reliable method for the assessment of immunosuppression among subjects with TB/HIV co-infection." (PMID 24560255, 2014). "Considering that CD4+ T cell was the major target of HIV and only a little specific CD4+ T cells was detected in the HCV infected individuals, it was reasonable that HCV only contribute a little to the global gene changes of CD4+ T cells in HCV/HIV co-infections." (PMID 24520951, 2014). "Further immune dysregulation may occur in HCV/HIV coinfection due to HCV-mediated immune activation and HIV-associated CD4 T cell loss." (PMID 25071758, 2014). "Because IL-27 actives naïve CD4+ T-cells, this difference implies that co-infection with HCV might have altered the expression profile of IL-27, disrupted the biological function of IL-27, or accelerated CD4+ T cell death." (PMID 24816922, 2014). "HCV coinfection may increase immune activation, leading to CD4 cell apoptosis in HIV-1-untreated patients and more rapid progression to severe immunodeficiency." (PMID 26316953, 2013). "Furthermore, the low sensitivity of FM for HIV-positive individuals, particularly those with low CD4 T cell counts, will limit the number of additional patients found in countries with high rates of co-infection." (PMID 24039780, 2013). "HIV-Leishmania coinfection in these patients may reproduce a vicious cycle leading to persistent immune derangement and paradoxical persistence of low CD4+ cell counts and parasitemia despite HAART and liposomal amphotericin B administration." (PMID 23718708, 2013).
co-infection (continued). "However, in HIV-HBV, HIV-HCV and HIV-HBV-HCV co-infections, the mean CD4 count were 250 cells/mm3, 274 cells/mm3 and 125 cells/mm3 respectively." (PMID 23721493, 2013). "In addition to the potential effects on CD4 cell counts, several studies have examined the impact of coinfection on the plasma HIV-1 viral load." (PMID 26316953, 2013). "Factors associated with increased risk of HAND in HIV patients with viral suppression on ART include older age, low CD4 nadir, active HCV co-infection, and cardiovascular risk factors, but the mechanisms underlying HAND and their relationship to systemic inflammation are poorly understood." (PMID 24259252, 2013). "Two interesting findings emerge from our study, firstly, among the foods rich in calcium yogurt was an independent protective predictor of BMD in HIV-subjects; second, HIV/HCV co-infection, drug addiction and nadir CD4+ T-cell count < 200 cells/μL were independent predictors of severe bone disease." (PMID 22894751, 2012). "The multivariable analysis took into account gender, age, route of HIV transmission, GSS of the backbone therapy, CDC stage C, duration of HIV infection, number of regimen changes, HBV/HCV coinfection, baseline CD4+ T cell counts, HIV-1 RNA, and baseline TG, TC and ALT levels." (PMID 22808029, 2012). "For patients with XDR-TB and HIV coinfection, multivariate regression analysis revealed several independent correlates of survival, including negative auramine sputum smear, CD4>200 cells/mm3 at diagnostic sputum collection, and the receipt of ART." (PMID 22412840, 2012). "Collectively, the results suggest that inhibitory KIR2DL2 and KIR2DL3, which are alleles of the same locus, play a role in the inverse effects on PM and PM/HIV co-infection, and the effect of KIR gene content polymorphisms on PM in HIV-1 women is dependent on high CD4 counts." (PMID 22715396, 2012). "Microbial translocation (MT) through the gut accounts for immune activation and CD4+ loss in HIV and may influence HCV disease progression in HIV/HCV co-infection." (PMID 22363790, 2012). "The results suggest that inhibitory KIR2DL2 and KIR2DL3, which are alleles of the same locus, play a role in the inverse effects on PM alone and PM/HIV co-infection and the effect of KIR gene content polymorphisms on PM in HIV-1 positive women is dependent on high CD4 cell counts." (PMID 22715396, 2012). "Diagnostics, staging, including CD4 cell count and viral load testing simultaneous with sputum smears and cultures, and therapy for both drug susceptible and drug-resistant TB and HIV-coinfection should ideally occur in the same setting, by the same practitioners." (PMID 22412840, 2012). "Lower CD4+ lymphocyte count was found to be the only predicting factor for co-infection." (PMID 22738361, 2012). "In both groups, HSV-2 co-infection rates decreased with higher CD4 counts." (PMID 21949704, 2011). "Among HIV-1 seropositive adults with CD4 counts above 250 cells/mm3 in Kenya, traditional risk factors for helminth infection, including rural residence and lack of education, were associated with co-infection, while lower CD4 counts were not." (PMID 20361031, 2010). "Since cavitation largely determines sputum bacillary grade, TB-HIV co-infection is also associated with higher likelihood of smear-negative disease, or low bacillary density in smear-positive disease, in proportion to CD4 count." (PMID 21605474, 2010). "Although recent studies of T-lymphocyte profiles in FIV-infected wild lions and pumas suggest that CD4 depletion occurs, our survey found that co-infection with FIV was present in 2 but absent in 3 FeLV-associated deaths." (PMID 18258118, 2008). "Immune enhancement strategies may be important in HCV/HIV co-infection to reduce the depletion of CD4+ cells thereby promoting both host defense mechanisms and enhanced responses to therapeutic regimens." (PMID 25977607, 2008).